CD4 (CD4 molecule)
Diseases named in the same sentence as CD4 in open-access papers (continued):
Sharing a sentence is not in itself a finding about the gene and the disease.
tumor (continued). "UPR-induced inflammation can be critical for anti-tumor immunity, since activated leukocytes can present tumor antigens to CD4+ T cells." (PMID 29796176, 2018). "In fact, in DSS-AOM-treated mice, transient ablation of CD4/Foxp3 Treg, during the carcinogenesis, suppressed tumor outgrowth and distribution, accompanied by an increased number of CD8 effector T cells." (PMID 29915171, 2018). "Tumour cells display TCRγ or β gene rearrangements and the TCRβ-chain is expressed on the surface in most cases, most notably in CD4+ cases." (PMID 30305106, 2018). "CD4+ T cells also play critical roles in anti-tumor responses as they indirectly stimulate CD8+ T cells by secreting pro-inflammatory cytokines that support CD8+ T cell activities." (PMID 30647853, 2018). "We show that Entinostat significantly increases the numbers of tumor-infiltrated CD8 and CD4 cells and reduces the frequency of immunosuppressive Tregs and MDSCs leading to a significant delay in tumor growth." (PMID 30400835, 2018). "The studies shows that Tregs cells is associated with the inhibition of both CD4+ and CD8+ T cells mediated immunity and this inhibition of CD4+ and CD8+ T cells within the tumor microenvironment reduces tumor immunity." (PMID 29662489, 2018). "HDACi enhance the immunotherapy response and augment immunotherapy with PD-1 blockade in melanoma cells, inhibit apoptosis of CD4+ T cells within the tumor, upregulate antitumor immune responses and restrict tumor growth." (PMID 29651407, 2018). "Both of these radiation plus dual immunotherapy studies documented elevated CD8+ and CD4+ T cells within the tumor of combined therapy-treated animals." (PMID 30854331, 2018). "NLRP3 signaling in macrophages drives the differentiation of CD4+ T cells into tumor-promoting Th2, Th17, and T-regulatory cell types, while suppressing Th1 cell polarization and cytotoxic CD8+ T cell activation." (PMID 30631327, 2018). "The Hf12-DBA with antibody group showed significant increase of tumor-infiltrating CD4+ T cells and CD8+ T cells in both the primary tumors and the distant tumors." (PMID 29907739, 2018). "Previous studies on CD4+ T cells has shown that they polarize to a type 17 phenotype (Th17) that exhibits stem cell-like memory qualities and yield greater tumour regression and persistence in vivo than other T helper subsets." (PMID 29996914, 2018). "LP cells indeed are antigen-selected mutating germinal centre (GC) B cells, express CD20, CD45, BCL6 and CD40 and are surrounded by CD4+ and PD-1+ T cells in the presence of follicular dendritic cell meshworks within tumour nodules." (PMID 29799516, 2018). "OXPHOS dependent immune cells include CD4+ regulatory T cells (Tregs), myeloid-derived suppressor cells (MDSC), and tumor associated macrophages (TAM)." (PMID 30400822, 2018). "Stratifying CD4+ T cells from LNs according to the patients’ pT stage revealed differences in methylation state relating to local tumour responses to NAC, which is correlated with disease progression." (PMID 30075815, 2018). "Compared with a-CTLA-4, treatment of tumor-bearing mice with a-CTLA4-TGFβRII resulted in a marked decline of FOXP3-expression in CD4+ cells." (PMID 29467463, 2018). "Analysis of tumors revealed a correlation between reduced tumor volume and increased CD4+ and CD8+ T-cell infiltrates in Dox-treated animals." (PMID 30413714, 2018). "The mechanism to enhance the homing of CTLs by helper peptide vaccines was reported to be due to the secretion of IFN-γ from the tumor infiltrating Th1 CD4+ T cells." (PMID 30542516, 2018). "Tumor-bearing mice were left untreated (control) or injected i.p. with anti-CD4 mAb on days 5 and 9 after tumor inoculation (aCD4)." (PMID 30733724, 2018). "Recently, growing evidence indicates that CD4+CD25+FOXP3+ regulatory T cells (Tregs) play a significant role in the control of tumor immunity, immune evasion and therapy resistance." (PMID 30079021, 2018).
tumor (continued). "By collecting single-cell suspensions of the orthotopic CT26-FL3 tumors, we found increased amounts of CD8+ T cells, CD4+ T cells, activated DCs and elevated PD-L1 expression in the tumor of OxP-treated mice as compared to PBS-treated mice." (PMID 29884866, 2018). "Recently, adoptive transfer of a CD4+ dominant T cell product resulted in tumor regression in a patient with metastatic cholangiocarcinoma and a complete durable remission in a patient with metastatic breast cancer." (PMID 30140266, 2018). "In particular, regulatory T cells (Treg) are proposed as key components of the immune suppressive tumor microenvironment with strong suppressive capacities toward CD4+ and CD8+ T lymphocytes, B cells, and dendritic cells etc.." (PMID 30619765, 2018). "Tumor-derived exosomes induce the conversion of CD4+CD25neg T cells into CD4+CD25highFOXP3+ Treg cells." (PMID 29720982, 2018). "Abundant expression of MHC class II can also lead to potent tumor-specific CD4 T cell responses that dampen cytotoxic CD8 T cell responses in a TNF-related manner." (PMID 29032503, 2018). "While ACT with CD8+ T cells has been more thoroughly studied, the impact of CD4+ T helper cells on tumor immunity has recently emerged both preclinically and clinically." (PMID 30140266, 2018). "Similar to that observed for CD3+ pan T cells, we observed that treatment with IL-12-LNP promoted a robust recruitment of CD4+ immune cells both into the tumor and surrounding normal liver tissue when compared to control mice treated with NST-LNP." (PMID 30458889, 2018). "Coculture with Panc02-OVA or E.G7-PD-L1 tumor cells also led to specific activation of CD4+ T cells." (PMID 30214445, 2018). "We demonstrated that the Gal-1 gene dosage did not affect tumour incidence, growth rate, or survival probability, but was correlated with alterations in the immune phenotype exemplified by a reduction of CD4+ T cell infiltration in tumours of Gal-1−/− mice." (PMID 29498681, 2018). "Treatment with HSCT in the early phase of tumor progression (group 2a) resulted in a reduction in the proportion of Treg cells among CD4+ T cells, although they were still elevated compared with non-tumor-bearing mice." (PMID 30057919, 2018). "A report shows that CD19+CD25+ tumor-evoked Breg (tBreg) cells induce TGF-β-dependent conversion of CD4+ T cells to Treg cells in breast cancer." (PMID 29762501, 2018). "In SVX-vaccinated mice bearing hCT26 tumor, we observed significant increased frequencies of both splenic and intra-tumoral CD4+ Tconv and CD8+ T cells, and decreased frequencies of Treg cells." (PMID 30483475, 2018). "Both animal studies and clinical trials in cancer patients showed that CD4 T cells specific to tumor-derived mutant peptides are essential for the efficacy of immune checkpoint blockade therapy by PD1 antibody." (PMID 30075702, 2018). "Specifically, IL-2/CD40 reduced expression of several regulatory molecules (CD39, A2AR, A2BR, PD-L1, ICOS, and/or IL-10) on young tumor-infiltrating CD11c+ cells and CD4+ T cells, suggesting reduced suppressive activity." (PMID 30560130, 2018). "Upon maturation, DCs migrate to nearby lymph nodes (LN), where they present tumor antigens and activate tumor-specific CD4+ and CD8+ T cells." (PMID 29751789, 2018). "Vaccination with the conjugates led to a strong infiltration of CD8+ T cells into the tumor while the percentages of CD4+ T cells in the tumor were similar to those in untreated mice." (PMID 30541631, 2018). "An investigation of tumor-infiltrating T cells showed that CD4+ T cells and Tregs were significantly decreased in elderly mice, whilst CD8+ T cells were similar with age." (PMID 30560130, 2018). "Bacterial infections also alter the function of different cellular components of the immune system, such as CD4+ and CD8+ T cells, myeloid-derived suppressor cells (MDSCs), regulatory T cells (Tregs), tumor-associated macrophages (TAMs), and their activation." (PMID 29765907, 2018).
tumor (continued). "Another subtype of T cells, such as regulatory T cells (Treg, CD4+ Foxp3+) create a highly immunosuppressive tumor environment through maintaining the expression of PD-1 on its surface." (PMID 28878676, 2017). "In this regard, Solitomab (MT110, AMG 110), an EpCAM/CD3-bispecific single-chain antibody, is able to bind polyclonal CD8+ and CD4+ T cells and activate them, addressing against EpCAM-expressing tumor cells." (PMID 28531111, 2017). "More recently CD4+ T cells have been pointed out to have more direct roles in cancer immunity with the description of tumor-reactive, cytotoxic CD4+ T cells." (PMID 29066810, 2017). "Despite these weaknesses, we documented that CD4+ naïve/memory ratio independently predicted tumor progression." (PMID 29137371, 2017). "CD25high CD127low Tregs on tumor-infiltrating CD4+ cells were significantly higher than those in both blood (21.54% vs. 7.54%, p < 0.0001) and paraneoplastic tissue (21.54% vs. 7.86%, p < 0.0001)." (PMID 29213216, 2017). "CCL5 has been implicated in the recruitment of CD4 + CD25 + Foxp3+ Tregs, leading to the generation of a suppressive environment that supports tumor tolerance." (PMID 29216863, 2017). "The Tregs are a subset of CD4+ T-cells with immune-suppressive cell type present in the tumor microenvironment." (PMID 28304339, 2017). "CD4+CD25+FOXP3+ regulatory T cells (Treg) inhibit the anti-tumour immune response and reduce the effect of cancer immunotherapy." (PMID 28253320, 2017). "All mature T cells express CD3+; CD3+ and CD4+ T cells are helper T lymphocytes that promote anti-tumor immunity." (PMID 28410575, 2017). "Unlike CD8+ T cells, which mediate the clearance of pathogens by destroying all infected host cells, CD4+ T cells secrete antiangiogenic cytokines to activate other T cells and recruit other tumoricidal myeloid cells to the tumor site." (PMID 29250133, 2017). "To further investigate the links between TH9 cells and autophagy in a cancer setting, we implanted B16-OVA tumour cells subcutaneously (s.c.)into control or Atg5fl/fl*CD4-Cremice." (PMID 28916785, 2017). "Flow cytometry analysis showed that a total number of CD45+ F4/80+ macrophages (p < 0.01), CD45+ CD11c+ CD11b+ inflammatory DCs (p < 0.05), and CD4+ helper T cells (p < 0.01) were significantly lower in the lungs of tumor-bearing mice that received MSCs." (PMID 28798777, 2017). "Previous studies have shown that IP10 chemoattracts CXCR3-positive lymphocytes to tumor areas, and promotes activation of CD4+ Th and CD8+ Tc lymphocytes." (PMID 28915590, 2017). "Patients who had limited tumor burden, better CD4 response or higher number of CEA specific T-cells appeared to benefit from the vaccine." (PMID 28085094, 2017). "The observed control of tumor growth in experimental tumor models harboring transposons for CD4 and CD8 neoepitopes also suggest a mechanistical role of CD4 and CD8 T cell interaction in cancer immunosurveillance." (PMID 29312332, 2017). "Th1 polarized CD4+ T helper cells, known for their ability to help in the promotion and maintenance of anti-tumor CTL responses, also secrete IFN-γ that recruits various cells of innate and adaptive immunity to tumor sites and promote their activation." (PMID 29283429, 2017). "It's reported that CD4+ T cells were required for the remodeling of the tumor microenvironment to sustain tumor regression." (PMID 28412743, 2017). "CD11b+Gr+ cells suppressed the proliferation of CD4+ T cells, indicating that CD11b+Gr+ cells in our tumor models possessed immunosuppressive activity and are functionally considered as MDSCs." (PMID 28894087, 2017). "Nevertheless, a review has also revealed that CD4 CTL affect both protective and pathogenic immunity, so the function of CD4 CTL on tumor cells in tumor microenvironment should be ulteriorly researched by more studies." (PMID 29029545, 2017).
tumor (continued). "Based on these studies, mechanisms through which CD4+ cells can undergo differentiation into Tregs under the influence of tumor microenvironment, with assistance of dendritic cells and the stromal component, have been proposed." (PMID 29075318, 2017). "In a mouse melanoma model, tumor-specific CD4+ effector T-cells showed traits of chronic exhaustion, with high expression levels of PD-1, TIM-3, 2B4, TIGIT, and LAG-3 inhibitory molecules." (PMID 28970830, 2017). "Tumor-specific CD4+ T cells acquire cytotoxic functions and eradicate tumor cells in vivo when these cells are transferred into lymphopenic hosts." (PMID 28854279, 2017). "As a mature marker restricted to the hematopoietic compartment, CD4 is an attractive target that restricts on-target, off-tumor effects to healthy CD4+ cells in the hematopoietic compartment." (PMID 29348865, 2017). "The results showed that miR-34a increased the number of tumor-infiltrating CD4+ cells and CD8+ cells and reduced the number of macrophages and Tregs." (PMID 28915924, 2017). "We determined that this therapeutic benefit of combinational treatment is due to a significant increase in tumor infiltrating effector CD4+ and CD8+ T cells along with a decrease of inhibitory cells." (PMID 28807056, 2017). "Altogether, these data demonstrate that combined anti-CD4/anti-PD-1 mAb immunotherapy induces tumor rejection through a CD8+ CTL response." (PMID 29070883, 2017). "Given that the development of Tregs is under the influence of various inductive signals, most importantly TGF-β1, we found a significantly increased population of CD4+ Foxp3+ Tregs in the tumor of 2cKO mice." (PMID 28592285, 2017). "FACS analysis revealed that 94.9% of the CD4+ T cells responding to tumor-specific stimulation were from transferred donor cells." (PMID 28854279, 2017). "Our previous data indicated that repeated s.c. injections of rIL-21 have a limited anti-tumor activity in the Neuro2a model, although the combination with an anti-CD4 mAb showed a potent synergistic effect." (PMID 29070883, 2017). "The TCR affinity required for the optimal anti‐tumour functionality of CD4+ T cells is higher than that required for CD8+ T cells." (PMID 27324616, 2017). "Flow cytometry analysis of single-cell tumor samples revealed that ~20% of the intratumoral CD4+ T cells were FoxP3+GFP+ Treg cells." (PMID 28496990, 2017). "Due to the variable expression of CD40 on a wide variety of immune cells, including CD4+ helper T-cells, macrophages and B-cells, activation of this pathway mediates anti-tumour immunity in a pleiotropic manner." (PMID 29157300, 2017). "For these reasons, RT is thought to act as an “in situ tumor cell vaccine”, whereby CD4+ and CD8+ T cell responses are generated through antigen release and acquisition by DC in the presence of the appropriate stimuli." (PMID 28134800, 2017). "It is therefore possible that the impaired tumor clearance we observed with PD-L1+ tumors is due in part to generation of immunosuppressive Tregs, and Pdcd1 deletion in CD4+ T cells abrogates this re-programming and enhances tumor clearance." (PMID 28389661, 2017). "As compared with the wild type, significant increase of CD4+ Foxp3+ Tregs population was found in the spleen, lymph nodes and peripheral blood of 2cKO tumor bearing mice." (PMID 28592285, 2017). "The correlation between Tregs and the tumor-infiltrating Tim-3+ PD-1+ CD4+/CD8+ T-cells was also examined." (PMID 29213216, 2017). "Collectively, these findings reveal that CD26int and CD26high T cells persist in the tumor to a greater extent than bulk CD4+ and CD26neg T cells." (PMID 29213079, 2017). "We found that the presence of CD4+CD25hiFoxP3+ T cells, which accumulate during culture, can suppress the expansion of tumor-reactive T cells." (PMID 28401257, 2017). "Conversely, decreased CDK5 expression enhanced the recruitment of CD4+ T-cells to the tumor site in mice, and increased the tumor-free survival rate of the mice." (PMID 28077789, 2017).
tumor (continued). "For example, agonist molecules such as DTA-1, a Rat IgG2b antibody specific for murine GITR, have been shown to be highly effective at promoting tumor rejection in specific tumor models and promoting potent antitumor CD4 and CD8 T cell responses." (PMID 28649380, 2017). "We found that in the epithelioid tumours, high CD4+ and CD20+ counts, and low FOXP3+, CD68+ and NP57+ counts linked to better outcome." (PMID 28817839, 2017). "CD4+ T cells are also found in the tumor microenvironment, the majority of which are regulatory T cells (Tregs) and Th17 cells." (PMID 28418870, 2017). "DCs bring the tumour antigens to peripheral lymphoid tissue, where they activate antigen- naïve CD4+ and CD8+ T cell responses." (PMID 29208938, 2017). "The interaction between CD4+ T cells and tumor cells is indirect in the sense that the tumor is suppressed through the action of cytokines." (PMID 29250133, 2017). "For example, dendritic cells (DCs) can capture and present antigens released by tumor cells; effector T cells (CD8+) and TAMs can dissolve and devour tumor cells; and helper T cells (CD4+), including FoxP3 Tregs, impose restrictions on immune response." (PMID 28977947, 2017). "For example, the shrinking RUQ tumor was heavily infiltrated with CD4 and CD8 T cells and had evidence of active CD8 T cell surveillance with expansion of specific TCR clonotypes." (PMID 28841418, 2017). "Preclinical and clinical results of HIFU tumor ablation show increased infiltration and activation of CD4+ and CD8+ T cells." (PMID 27585790, 2017). "In these tumor models, CD4+ T cells were strictly necessary for the anti-tumor effects of anti-PD-1 mAb therapy as their depletion abrogated the therapeutic activity." (PMID 29070883, 2017). "When Cyclophosphamide was combined with cryoablation in a murine colorectal model, the proliferation of tumor specific T cells was greatly increased as was the ratio of effector CD4+ T cells to regulatory FoxP3+ T cells." (PMID 29037259, 2017). "Pembrolizumab is a monoclonal IgG4 antibody directed against PD-1, which blocks the immunosuppression mediated by the interaction of PD-L1 on tumor cells and PD-1 on CD8+ and CD4+ T cells, therefore, improving tumor cell recognition by T cells." (PMID 28238174, 2017). "FACS analysis demonstrated that the majority of the tumor-specific CD4+ T cells were from transferred donor T cells (85.7%)." (PMID 28854279, 2017). "Significantly, DTA-1 treatment changed the frequency of many dominant Treg and CD4+Teff clones in tumor infiltrates, Tregs being more strongly affected than CD4+Teffs." (PMID 28638937, 2017). "It has been shown that the tumor infiltration by CD4+ and CD8+ T cells and dendritic cells was increased after bevacizumab treatment and that the antigen-presenting capacity of dendritic cells was augmented." (PMID 29250196, 2017). "Using two well‐studied HLA A2‐restricted tumour systems, CD4+ T cells transduced with enhanced affinity TCRs were shown to be potent effector cells in response to cognate antigen and exhibited direct tumour lysis." (PMID 27324616, 2017). "The shTGFβ1-1 LVs treatment caused also enhanced influx of CD4+ and NK (CD49b+CD8−CD4−) cells into tumor nodules, which was additionally enlarged by BMDC/TAg treatment." (PMID 28713366, 2017). "The tumor-promoting effects of MSCs were accompanied by a marked increase in CD4+ cells, CD11b+ cells, CD4+Foxp3+ Tregs, and CD11b+Ly6C+Ly6G− MDSCs." (PMID 29029511, 2017). "Specifically, CD4+ CD25+ T-regulatory cells (or Tregs) have been shown to suppress anti-tumor immune responses by CD8+ T cells." (PMID 29021522, 2017). "Concomitantly, increased CD4+ and CD8+ T cell numbers, as well as reduced proportion of CD4+CD25+FoxP3+ (Treg) cells were observed in tumor draining lymph nodes (TdLN)." (PMID 29296231, 2017).